YTHDF2 (YTH N6-methyladenosine RNA binding protein F2)
Diseases named in the same sentence as YTHDF2 in open-access papers (continued):
Sharing a sentence is not in itself a finding about the gene and the disease.
tumor (continued). "YTHDF2 has been shown to affect tumor development in certain cancers by degrading m6A-modified mRNAs by binding to m6A sites." (PMID 34512342, 2021). "They used an orthotopic transplantation model to clarify the role of YTHDF2 in promoting tumour metastasis and found that YTHDF2 expression was negatively correlated with patient survival." (PMID 34246319, 2021). "For example, in lung cancer, YTHDF2 promotes the tumor cell growth by binding directly to the m6A-modified site in the 6-phosphogluconate dehydrogenase (6PGD) 3’-UTR." (PMID 34105069, 2021). "YTHDF2 inhibits inflammasome-mediated tumor vascularization and malignancy by degradation of m6A-containing serpin family E member 2 (SERPINE2) and interleukin-11 (IL-11) mRNA." (PMID 33692959, 2021). "It is hoped that this study would lead to a better understanding of the possible role of YTHDF2 in tumor immunology and its prognostic value in KIRC." (PMID 34512342, 2021). "According to the expression level of YTHDF2, these tumor specimens were categorized into two groups and the clinicopathological features of each group were analyzed." (PMID 33658012, 2021). "In terms of mRNA levels, TRMT6, TRMT61A, TRMT61B, TRMT10C, YTHDF1 and YTHDF2 YTHDF3 were overexpressed in tumor sample." (PMID 34777359, 2021). "CCK-8, colony formation, tumor sphere formation, EdU, flow cytometry and Transwell assays were performed to illuminate the impact of YTHDF2 to the behavior of UOK109 cells." (PMID 33741027, 2021). "Several studies indicate that YTHDF2 can perform either as an oncogenic protein or as a tumor suppressor relying on the context of different cancers or by regulating different mRNA targets." (PMID 33658012, 2021). "It was interesting that YTHDF2 was up-regulated or down-regulated in different cancers, and played an oncogenic role or acted as a tumor suppresser." (PMID 33593354, 2021). "The expression of FTO and YTHDF2 can be influenced by tumor heterogeneity, hypoxia, and post-translational modification." (PMID 33390849, 2021). "We further verified the expression levels of YTHDF2, GSK3β, β‐catenin and Cyclin D1 in 150 pairs of tumour and ANTs." (PMID 34709763, 2021). "Nevertheless, YTHDF2 is also capable to suppress cell proliferation, tumour growth and activation of MEK and ERK signalling via promoting the degradation of EGFR mRNA in HCC cells." (PMID 33461542, 2021). "In detail, METTL3-mediated m6A modification repressed the suppressor of cytokine signaling 2 (SOCS2), which acted as a tumor suppressor in HCC via YTHDF2-mediated mRNA degradation." (PMID 33593354, 2021). "The mRNA and protein levels of YTHDF2 were higher in the NSCLC normal tissues than in their paired tumor tissues." (PMID 32106857, 2020). "One possible explanation is that when YTHDF2 interacts with tumor suppressor genes then promotes cell growth." (PMID 32106857, 2020). "Until very recently, more and more researches reported that YTHDF2 induced decay of targeted mRNAs was involved in several tumor progressions." (PMID 33121495, 2020). "Evidence has shown that YTHDF2 can act as an oncogene or tumor suppressor in different tumor models." (PMID 33015074, 2020). "To analyze YTHDF2 expression in ccRCC and tumor-adjacent normal tissues, we extracted and compared YTHDF2 gene expression from the TCGA database, including 529 ccRCC tumor tissues and 72 tumor-adjacent normal tissues." (PMID 33102202, 2020). "YTHDF2 was recently recognized as a tumor suppressor, in which proliferation and angiogenesis were impaired by YTHDF2 overexpression." (PMID 33363211, 2020). "The m6A modification catalysed by METTL3 is recognized by YTHDF2 to mediate the mRNA decay of tumour suppressors SETD7 and KLF4, which consequently induces the BCa progression." (PMID 32126149, 2020). "For the m6A methylation readers, the expression of HNRNPC, YTHDF1, and YTHDF2 was also significantly increased in higher tumor grade and stage." (PMID 32850303, 2020).
tumor (continued). "It has been confirmed that YTHDF2 induced the targeted degradation of the tumor suppressor SOCS2 to promote tumor progressions of HCC, and this regulation was dependent on METTL3-induced m6A modifications." (PMID 33121495, 2020). "After tumor purity-correlated adjustments, we found a significant correlation between YTHDF2 expression and most marker genes of various types of immune cells and different functional T cells in LIHC." (PMID 33344502, 2020). "Immunohistochemical staining was performed on the tumor body of MGC-803 to verify the expression of YTHDF2." (PMID 33505426, 2020). "In summary, our study demonstrates that the overexpression of KDM5A has a tumor-supporting effect on PCa, as it suppresses the YTHDF2-dependent MOB3B expression by binding to miR-495." (PMID 33087165, 2020). "Given that YTHDF2 facilitates tumor proliferation but prohibits migration, we compared the level of YTHDF2 in tumor tissues in different T and N stages." (PMID 33062408, 2020). "A nude mouse heterogeneous tumor model was used to detect the effect of YTHDF2 on subcutaneous tumor formation of GC cells." (PMID 33505426, 2020). "As a main cytoplasm m6A reader, YTHDF2 has been reported to degrade the m6A-modified mRNAs by binding to m6A sites to promote the tumor progression in several cancers." (PMID 33121495, 2020). "We observed that the transcripts of METTL3 and YTHDF2 were promoted in primary tumours compared to normal subjects." (PMID 32126149, 2020). "Correlations between YTHDF2 and infiltration of immune cells were investigated by Tumor Immune Estimation Resource (TIMER) and GEPIA." (PMID 33344502, 2020). "In the normal group vs. all tumor groups, the area under the ROC curve (AUC) of YTHDF2 was 0.65 in the GTEx + TCGA-LIHC, and ICGC-LIRI cohorts." (PMID 33344502, 2020). "We used the Tumor Immune Estimation Resource (TIMER) database to study differences in YTHDF2 expression in tumor tissues and adjacent normal tissues." (PMID 32986017, 2020). "We also investigated the relationship between YTHDF2 expression and tumor-infiltrating immune cells (TIICs) in various cancers." (PMID 32986017, 2020). "The mRNA expression level of YTHDF2 was evidently decreased in ccRCC (N = 529) as compared with tumor-adjacent normal tissues (N = 72, P = 0.0086)." (PMID 33102202, 2020). "Phosphorylated AKT was consequently confirmed as the downstream of METTL3/YTHDF2/LHPP/NKX3–1 to induce tumor proliferation and migration." (PMID 33121495, 2020). "YTHDF2 deficiency robustly facilitated HCC growth and metastasis, suggesting that YTHDF2 is a tumor suppressor in HCC." (PMID 33072775, 2020). "We examined the expression of 17 m6A-related genes in GEO database, and found that WTAP, RBM15, YTHDF1, and YTHDF2 were differently expressed in tumor tissue compared with control tissue." (PMID 32814762, 2020). "Particularly, in contrast to their low CNV frequencies (< 5%) in normal samples, CBLL1, METTL14, RBM15, IGF2BP1, YTHDC1, and YTHDF2 exhibited more than 20% difference in their frequencies of CNVs between tumor and normal samples." (PMID 33585234, 2020). "Highly expressed YTHDF2 promotes tumor proliferation by activating the AKT/GSK3 β/cyclin D1 pathway and suppresses migration and invasion by binding m6A sites on and decomposing yes-associated protein (YAP) mRNA." (PMID 33062408, 2020). "The tumor-promoting effect of METTL3 was also reflected by its activity to mediate YTHDF2-dependent mRNA decay of SOCS2, a suppressor of cancer metastasis." (PMID 33584787, 2020). "YTHDF2 loss facilitated the expression of MYC and CEBPA by increasing their stability, and also affected the sensitivity of leukemia cells to the tumor suppressor R-2-hydroxyglutarate (R-2HG)." (PMID 32276589, 2020). "During the observation of flank xenograft in BALB/c nude mice for 40 days, we found that knocking down YTHDF2 resulted in a dramatic retardation of tumor growth, which was consistent with the radiance value tested by an in vivo imaging system." (PMID 33121495, 2020).
tumor (continued). "In HCC cells, YTHDF2 can be specifically restricted by hypoxia and act as a tumor suppressor with inhibitory effect on tumor growth." (PMID 31921664, 2019). "Mechanistically, YTHDF2 inhibited STAT3 phosphorylation and tumor growth by degrading IL11 mRNA, which encodes the dominant IL-6 family cytokine that endows gastrointestinal cancers with proliferative and invasive capacity." (PMID 31735169, 2019). "Strikingly, YTHDF2 also benefited tumor vessel normalization, as characterized by a positive correlation to pericyte coverage and an inverse correlation to vascular permeability." (PMID 31735169, 2019). "We show that YTHDF2 is required for suppressing tumor angiogenesis in vitro and in vivo, and restricting formation of vascular mimicry in the metastatic MHCC97H tumors." (PMID 31735169, 2019). "In this context, we unexpectedly found that YTHDF2 resisted either tumor angiogenesis or vascular mimicry by targeting SERPINE2." (PMID 31735169, 2019). "Despite the sensitivity of destabilizing IL11 and SERPINE2 mRNAs in response to tumor hypoxia, YTHDF2 expression is readily silenced in the presence of active HIF-2α." (PMID 31735169, 2019). "Hypoxic tumor areas showed relatively low YTHDF2 expression in the xenograft mouse model, providing an in vivo evidence for hypoxia-mediated YTHDF2 reduction." (PMID 31735169, 2019). "Our results indicate that YTHDF2 represses both tumor cells and tumor vasculature by processing IL11 and SERPINE2 mRNAs to decay." (PMID 31735169, 2019). "In various tumor cells, YTHDF2 has been found to regulate immune escape." (PMID 41522342, 2026). "Through an m6A-dependent mechanism, YTHDF2 promotes nascent RNA synthesis, stabilizes RNA homeostasis, and regulates mitochondrial function and chromatin remodeling, thereby preserving T-cell polyfunctionality and anti-tumor activity." (PMID 41403953, 2025). "Furthermore, YTHDF2 orchestrates the reprogramming of tumor-associated macrophages in the tumor microenvironment (TME), and YTHDF2 is an effective target to enhance cancer immunotherapy." (PMID 40704992, 2025). "Furthermore, down-regulation of YTHDF2 reduces degradation of tumor-promoting factors IL11 and SERPINE2 mRNA, thereby facilitating tumor development." (PMID 41446042, 2025). "Modulation of YTHDF1 or YTHDF2 activity could reshape the tumor immune microenvironment by influencing antigen presentation, cytokine production, and immune cell infiltration." (PMID 41403953, 2025). "Ythdf2 deficiency under IL-4 and TGF-β signaling promotes Th9 differentiation and enhances IL-9 and IL-21 secretion, thereby improving CD8+ T-cell and NK-cell infiltration and cytotoxicity, ultimately strengthening anti-tumor immunity." (PMID 41403953, 2025). "YTHDF2 also functions as a tumor-intrinsic regulator of immune evasion." (PMID 41403953, 2025). "In highly malignant glioblastoma, YTHDF2 disrupts cholesterol metabolism by recognizing m6A modifications on the key cholesterol metabolism factor LXRα and facilitating its degradation, significantly promoting tumor cell proliferation." (PMID 41446042, 2025). "The role of YTHDF2 in PDE1A-driven tumor metastasis should be elucidated in future studies." (PMID 40704992, 2025). "In addition, sh‐YTHDF2 and DNase I inhibited NETs formation in tumour, increased CD8(+) T cells activity, and inhibited LUAD growth." (PMID 39865544, 2025). "For instance, YTHDF2 may promote tumor progression by enhancing M2-like macrophage polarization, yet also restrain immunosuppression by modulating CD8+ T cell exhaustion or MDSC activity." (PMID 41403953, 2025). "The seemingly contradictory roles of YTHDF1 and YTHDF2 in tumor immune regulation may arise from their context-dependent functions and cell-type specificity." (PMID 41403953, 2025). "In addition, inhibition of TLR3 also reversed the tumor-promoting effect of YTHDF2 knockdown in mice from A431 cells." (PMID 41224760, 2025).
tumor (continued). "Notably, we were particularly intrigued by YTHDF2 due to its fundamental involvement in protein phase separation and its strong correlation with tumor cell proliferation." (PMID 41472850, 2025). "Therefore, the THM/YTHDF2 pathway not only regulates autophagy but also affects the tumor immune microenvironment by altering PD-L1 expression, thereby potentially improving the efficacy of immunotherapies." (PMID 40756353, 2025). "While Treg-specific Ythdf2 loss does not disrupt peripheral immune homeostasis, it increases apoptosis and impairs suppressive activity of intratumoral Tregs, thereby slowing tumor progression." (PMID 41403953, 2025). "Furthermore, YTHDF2 was lower in stage 2 SCC than stage 1 SCC, suggesting an active role for YTHDF2 in skin tumorigenesis as well as tumor progression." (PMID 41224760, 2025). "YTHDF2 is upregulated in NK cells upon cytokine stimulation, tumor challenge, or viral infection." (PMID 41403953, 2025). "This highlights YTHDF2 as a critical regulator of intratumoral Tregs, whose selective targeting may enhance anti-tumor immunity while minimizing systemic autoimmunity." (PMID 41403953, 2025). "Furthermore, a small molecule degrader of YTHDF2 exhibits robust anti-tumor activity as monotherapy and synergizes with PD-1/PD-L1 blockade, highlighting YTHDF2 as a potential therapeutic target." (PMID 41403953, 2025). "The role of YTHDF2 in tumor progression has been well-studied." (PMID 39136000, 2024). "YTHDF2 was upregulated in lung adenocarcinoma and was found to degrade axis inhibition protein 1 (AXIN1), which encodes a negative regulator of the Wnt/β-catenin signaling, eventually leading to Wnt/β-catenin activation and tumor progression." (PMID 38503745, 2024). "However, the beneficial function of YTHDF2 in the immune response to tumor cells has been recently discovered." (PMID 39136000, 2024). "However, highly expressed YTHDF2 in lung cancer affects tumor malignant progression by promoting the stability of 6PGD mRNA." (PMID 38798700, 2024). "Moreover, the establishment of stable cell lines expressing WT or mutant YTHDF2 further stressed the importance of SUMOylation in suppressing EBV lytic replication in multiple EBV-infected tumor cells." (PMID 38236021, 2024). "Moreover, in vivo, YTHDF2-depleted tumors exhibited distinct margins with significantly reduced invasive tumor areas." (PMID 38398118, 2024). "YTHDF2 acted as a tumor promoter by upregulating PD‐L1 and VEGFA expression in HCC." (PMID 38247171, 2024). "Contrastingly, xenografts overexpressing YTHDF2 exhibited accelerated tumor progression." (PMID 39593172, 2024). "In different cellular contexts, the poised balance between mRNA degradation and translation may be altered and the role of YTHDF2 may shift from a tumor‐promoting role to a tumor‐suppressing role." (PMID 38247171, 2024). "This suggests that Ythdf2 plays a crucial role in the anti-tumor function of NK cells." (PMID 39439794, 2024). "However, in contrast to control counterparts, Ythdf2/Mettl3‐KO tumour cells were notably rejected in immunocompetent mice." (PMID 39568154, 2024). "Additionally, inhibition of UBXN1 by YTHDF2 induced NFκB activation, which promoted cell proliferation and tumor growth." (PMID 38398118, 2024). "For example, YTHDF2 (m6A reader) overexpression drives extrinsic radioresistance of tumor cells." (PMID 38970106, 2024). "In addition, overexpression of YTHDF2 reduced the infiltration of CD8+ T cells in the tumor immune microenvironment in HCC." (PMID 38247171, 2024). "Moreover, the increased tumor size and lung metastatic foci induced by YTHDF2 overexpression were impaired after inhibiting PD‐L1 or VEGFA expression in Hepa1‐6 cells, and these effects were most obvious when both PD‐L1 and VEGFA were downregulated." (PMID 38247171, 2024).
tumor (continued). "Similarly, compared to the control group, tumors in the sh-C + YTHDF2 group had larger volumes with unclear boundaries between tumor tissue and surrounding normal brain tissue, while the opposite was observed in the sh-C + sh-YTHDF2 group." (PMID 38637831, 2024). "In contrast, YTHDF2 might serve as a tumor suppressor in HCC development, as two studies provided evidence for hypoxia-mediated YTHDF2 reduction." (PMID 38545555, 2024). "However, degradation of circ_0003215 by YTHDF2 blocks this pathway and increases tumor progression through promoting metabolic reprogramming." (PMID 38075202, 2024). "Additionally, the overexpression of YTHDF2 significantly increased both tumor volume (P = 0.0063) and tumor weight (P = 0.0076)." (PMID 37012388, 2023). "Our study demonstrated that circFUT8 could interact with both YTHDF2 and miR‐186‐5p to function as a tumor oncogene dependent on the parent protein of FUT8." (PMID 37669906, 2023). "Another study showed that FBW7 inhibited tumor development by promoting YTHDF2 degradation." (PMID 37151889, 2023). "Since YTHDF2 destabilized LATS1 mRNA by reading the m6A methylation in LATS1, we predicted that deleting the expression of YTHDF2 could promote the tumor-suppressive effects of LATS1." (PMID 36609396, 2023). "YTHDF1 and YTHDF2 knockdown enhanced PD-L1 expression in tumor cells." (PMID 36810108, 2023). "However, YTHDF2 participates in anti-tumor and anti-viral infection by regulating the maturation, proliferation, and effector functions of NK cells." (PMID 36999016, 2023). "In addition, in vivo assay showed that overexpression of YTHDF2 rescued the tumor suppression induced by the HSP90β‐KD or overexpression of STUB1 in HepG2 xenografts." (PMID 37515378, 2023). "Consistent with this hypothesis, tumor proliferation, survival, and invasion were inhibited by YTHDF2 depletion, and this tumor suppressive effect was rescued by inhibiting the expression of LATS1." (PMID 36609396, 2023). "The discrepancy in the effect of YTHDF2 on HCC may be due to different cellular microenvironments or tumor heterogeneity." (PMID 36999016, 2023). "The correlation between YTHDF2 and tumor immunotherapy has attracted considerable attention." (PMID 36810108, 2023). "In vitro radiosensitivity rescue experiments showed that the radiosensitivity induced by ALKBH5 or YTHDF2 could be reversed by circAFF2, which was confirmed in grafted tumours." (PMID 37381158, 2023). "The catalytic subunit of protein phosphatase 2A (PP2A), PPP2CA, might mediate the tumor-suppressor roles of YTHDF2 in an m6A-independent manner." (PMID 36870954, 2023). "Notably, the latest study indicated that YTHDF2 was upregulated in prostate cancer and mediated tumor suppressors LHPP and NKX3-1 mRNA degradation in m6A-dependent way." (PMID 37598390, 2023). "Downregulated YTHDF2 is critical for inhibited tumor progression of HCC." (PMID 36810108, 2023). "Furthermore, YTHDF1 plays a tumor-promoting role by facilitating mitosis-associated RANBP2 mRNA translation in an m6A-mediated approach, while YTHDF2 exerts the same role by degrading the tumor suppressor GAS5 mRNA." (PMID 36999016, 2023). "However, the biofunction of YTHDF2 is heterogeneous in cancers, with some studies demonstrating its tumor-inhibiting function." (PMID 37012388, 2023). "Conversely, YTHDF2 is also considered a tumor-promoting factor in HCC." (PMID 36999016, 2023). "YTHDF2 plays controversial roles in different kinds of tumor." (PMID 37438359, 2023). "Our results suggested that YTHDF2 might play an important role in tumor immunity and serve as a predictive marker for immunotherapy." (PMID 36120577, 2022). "Notably, the tumor growth was inhibited in LV‐sh‐YTHDF2 infection group, and TMZ treatment further exacerbated this inhibitory effect." (PMID 35582627, 2022). "Moreover, YTHDF2 upregulation promoted tumor growth and increased tumor volume in vivo compared with control cells." (PMID 34996459, 2022).